INS (insulin)
Diseases named in the same sentence as INS in open-access papers (continued):
Sharing a sentence is not in itself a finding about the gene and the disease.
Insulin resistance (continued). "Moreover, our study showed that the serum insulin concentration and insulin resistance were higher in NWO compared to non-NOW; however, insulin sensitivity was lower in NWO." (PMID 29299442, 2017). "Although most studies found no improvement in glucose/insulin metabolism, others reported a significant reduction in FBG levels, fasting insulin or insulin resistance and HbA1c." (PMID 28657613, 2017). "However, the levels of fasting insulin were higher in normal-control versus ORX-control; GEB increased these levels in a dose-dependent manner, but HOMA-IR, an index of insulin resistance, was not different among the groups." (PMID 28607572, 2017). "This may indicate that, unlike Type 2 diabetes where the failure to increase insulin secretion by the beta cells is an important factor to the onset of the disease, in patients with BSCL, the increasing insulin resistance appears to be the key determinant." (PMID 26985241, 2016). "Indeed, when challenged with a single dose of glucose (2 g/kg) or insulin (1 U/kg), miR-150KO mice on HFD, but not on LFD, exhibited severe glucose intolerance and insulin resistance compared to wild type mice." (PMID 26833392, 2016). "Noteworthily, following 6 months of adalimumab therapy, a statistically negative correlation between TBS values and insulin resistance (measured by HOMA; r = −0.445; p = 0.02) and a positive one between TBS and insulin sensitivity (QUICKI; r = 0.497; p = 0.01) were found." (PMID 27293954, 2016). "A correlation occurred between age and fasting blood glucose (rs= 0.37, p=0.045) but fasting blood insulin levels and HOMA-IR index (an index of insulin resistance) were not significantly correlated with age (fasting insulin, rs=0.03, p=0.84; HOMA-IR: rs=0.22, p=0.28)." (PMID 28039490, 2016). "This paradoxical similarity in FID and ET‐1 response to insulin between LHCs and T2DM subjects suggests either absence of vascular insulin resistance in T2DM or transient development of vascular insulin resistance in LHCs under conditions of acute hyperinsulinemia." (PMID 27796268, 2016). "Additionally, our work indicates that the absence of functional B and T cells does not provide protection against HFD-induced insulin resistance as SCID mice fed on a HFD, although already insulin resistant, developed even greater glucose intolerance." (PMID 27026807, 2016). "There were no observed changes in insulin sensitivity among the different genotypes and thus the authors concluded that DGAT2 may play a role in mediating a disconnection between insulin resistance and hepatic steatosis." (PMID 26978356, 2016). "In agreement with our expectation, the mice under HFD+VDD feeding generated significant amount of glucose intolerance and insulin resistance, as determined by intraperitoneal glucose tolerance test (IPGTT) and intraperitoneal insulin tolerance test (IPITT) (data not shown)." (PMID 27895587, 2016). "Insulin sensitivity as determine by HOMA-IR scoring has not been developed for dolphins and the use of a hyperinsulinemic–euglycemic clamp to define insulin resistance in these animals is very invasive and not reasonable given the protections afforded these animals." (PMID 27148164, 2016). "Actually, a much lower dose of honokiol or magnolol (17 mg/kg once per day for 16 weeks) could effectively ameliorate the insulin resistance of HFD fed mice, although fasting blood glucose and plasma insulin levels were not improved." (PMID 27669240, 2016). "Results showed the statistically significant positive effects of resveratrol versus placebo/control for systolic blood pressure, HbA1C, and creatinine, but not for fasting glucose, homeostatic model assessment of insulin resistance (HOMA index), diastolic blood pressure, insulin, and lipid profiles." (PMID 26157708, 2015).
Insulin resistance (continued). "Plasma insulin levels were also assessed at the 14-week time point and showed a significant elevation in the WD-fed groups irrespective of AAB, indicating a level of insulin resistance induced by the WD." (PMID 25750189, 2015). "However, we did not confirm aggravation of insulin resistance in PCOS in comparison to controls, although both groups were markedly insulin resistant." (PMID 25878664, 2015). "Interestingly, both markers correlated well with glucose levels, although not with insulin levels, during the OGTT, which indicates that they are appropriate for predicting glucose tolerance, although not for predicting insulin resistance." (PMID 26132231, 2015). "However, the use of fasting BG and insulin was justified by the fact that HOMA-derived parameters are strongly related to clamp-measured insulin sensitivity and insulin resistance in subjects both with and without DM." (PMID 26655187, 2015). "Consequently, the suppression of hyperglycemia is more likely to involve increased insulin secretion by enhanced function and mass of β-cells in ZDF rats, rather than improvement of insulin resistance and sensitivity." (PMID 26379244, 2015). "Therefore, DBcAMP did not impact on insulin levels and it is plausible that by increasing hepatic cAMP levels led to a decrease of GSH and consequently to a state of postprandial insulin resistance." (PMID 25961284, 2015). "Our study’s negative correlation between fasting insulin and TAOS, such as, between HOMA-R and TAOS suggests that insulin resistance may have an unfavorable effect on anti-oxidant defense system in PCOS." (PMID 26330853, 2015). "Overall, the improvement in insulin tolerance was greater than that observed in glucose tolerance tests suggesting that 2-PCPA probably protected against HFD-induced adipose and skeletal muscle insulin resistance but not liver insulin resistance." (PMID 24586592, 2014). "Winocur and collaborators suggested that the stability of GLUT4 expression is related to the insulin resistance of fa/fa Zucker rats, because GLUT4 translocation to the plasma membrane can no longer be triggered by insulin signaling as it is in a normal metabolic context." (PMID 25278856, 2014). "However, after adjustment with insulin resistance index (HOMA-IR), fasting glucose, or insulin levels (data not shown), the significant difference in TRX-1 values between groups disappeared." (PMID 24689038, 2014). "Due to the insulin antagonizing effects of GH and the insulin sensitizing effects of IGF-I, these alterations are likely to have a negative effect on whole body insulin resistance and they may also contribute to the development of long-term complications." (PMID 24725803, 2014). "Similarly, glucose-stimulation of insulin, but not GIP, secretion was elevated in pregnancy, helping to maintain normal glucose tolerance despite coexistent insulin resistance." (PMID 24236022, 2013). "IMCL levels can serve as useful indices of insulin resistance/metabolic abnormalities in non-vertebrates, and vertebrates, including obese and/or type 2 diabetic patients, where increased IMCL levels are due to impaired insulin-stimulated glucose uptake." (PMID 24098655, 2013). "At later time points (6, 12, and 24 h) insulin was not able to increase IRS-1 tyrosine phosphorylation, indicative of insulin resistance, although this effect is partially explained by an LPS-induced increase in basal IRS-1 tyrosine phosphorylation (6 and 12 h)." (PMID 23704966, 2013). "The pathway linking insulin production to cancer outcomes independent of glycemic control and insulin resistance is suggested to involve tumorigenesis driven by increased insulin, IGF 1 and IGF 2, collectively signaling through both insulin and IGF-1 receptors." (PMID 23405181, 2013).
Insulin resistance (continued). "Fourth, HOMA-IR reflects insulin resistance in the liver rather than in fat and muscle, and it is a relatively indirect method of measuring insulin resistance compared with the oral glucose tolerance test (OGTT) and the euglycemic insulin clamp test." (PMID 24069257, 2013). "Fattah and Darwish concluded that there was a significant difference in the serum insulin level and HOMA-IR between PCOS, HI, and control groups, but in contrast with our results, there was not any difference in respect to insulin resistance between PCOS and HI groups." (PMID 24228029, 2013). "Insulin resistance in adipocytes and hepatocytes could further accentuate the negative effects of PDE3 inhibitors in these cells, because insulin utilizes PDE3B to antagonize the effects of catecholamines/cAMP." (PMID 23493150, 2012). "Insulin resistance can also be triggered by the presence of metabolic stressors, such as high blood non-esterified fatty acids (NEFA) levels, which compromises insulin sensitivity by reducing the action of this hormone in peripheral tissues, such as the liver, skeletal muscle and adipose tissue." (PMID 22347618, 2012). "Rstn has been shown to confer glucose intolerance and insulin resistance, and although no receptor for Rstn has been identified, induction of SOCS3 intracellularly has been suggested as a potential mechanism by which Rstn inhibits insulin signaling." (PMID 22815920, 2012). "Notably, increased daily intake of milk but not meat significantly elevated fasting insulin and IGF-1 serum concentrations and increased insulin resistance in 8-year old boys." (PMID 22891897, 2012). "However, HOMA insulin resistance was not significantly different between B1 and SR5, suggesting that hepatic insulin sensitivity was not influenced by sleep restriction, although subtle changes in insulin resistance would not be detected by the HOMA method." (PMID 22844441, 2012). "We found that men with metabolic complications that include peripheral insulin resistance, with or without well-controlled HIV infection, have altered myocardial glucose utilization per unit insulin and left ventricular relaxation and that these alterations appear to be interrelated." (PMID 22151886, 2011). "The performance of hyperinsulinemic–euglycemic clamp, the gold standard for investigating and quantifying insulin resistance, revealed that the consumption of the HFC diet aggravated HF-induced reduced GIR, whereas HFR-fed rats showed no impairment of insulin action compared with control rats." (PMID 20064776, 2010). "However, insulin levels and HOMA-IR index still remained in the normal range in SGA subjects during the first year of age, suggesting that no insulin resistance develops during this period and that insulin alone does not explain changes in adiponectin levels." (PMID 20298581, 2010). "We conclude that altered insulin activation of the PI3K/Akt but not the MAPK pathway precedes and may contribute to development of whole-body insulin resistance and type 2 diabetes in men with LBW." (PMID 19011679, 2008). "Insulin levels were higher in the obese, but HOMA insulin resistance scores did not vary." (PMID 18275595, 2008). "Our findings revealed that the primary metabolites reflective of FINDRISC were generally consistent with those influenced by fasting insulin and HOMA-IR but not FBG, suggesting that FINDRISC may reflect insulin resistance rather than glycemia per se from a molecular perspective." (PMID 40200054, 2025). "The Homeostasis Model Assessment of Insulin Resistance (HOMA-IR) index stands as a widely recognized tool for evaluating β-cell function and IR, nonetheless, its applicability is limited in patients receiving insulin treatment and in those with non-functional β-cells." (PMID 40164755, 2025).
Insulin resistance (continued). "However, this does not mean that FGF21 is not helpful for diabetes and insulin resistance in humans, and FGF21 analogs can improve the insulin signaling pathway by improving lipid metabolism and reducing lipotoxicity and chronic inflammation associated with obesity in humans." (PMID 40881124, 2025). "Moreover, serum RBP4 levels decreased in people in whom exercise improved insulin sensitivity, but not in those people in whom this effect was not achieved, indicating an RBP4-mediated link between a physically inactive lifestyle and insulin resistance." (PMID 38966226, 2024). "Finally, due to the absence of serum insulin levels, HOMA-IR, which is another insulin resistance surrogate, could not be compared." (PMID 38297286, 2024). "Besides, the homeostasis model assessment estimated insulin resistance (HOMA-IR) index, a marker to detect β-cell function and IR, is widely used, whose practical value is greatly limited in patients receiving insulin treatment or not having functional β-cells." (PMID 38184591, 2024). "Differently, fasting insulin levels and HOMA-IR showed a negative trend with EO exposure, which may suggest a potential mechanism whereby EO exposure impacts insulin secretion by pancreatic β-cells rather than promoting insulin resistance." (PMID 39647865, 2024). "However, TSH levels are also closely related to insulin resistance in women with PCOS, regardless of age or BMI, and TSH a cutoff of ≥2 mIU/L may be considered a specific predictor of insulin sensitivity in patients with PCOS." (PMID 37635968, 2023). "Skeletal muscle is the major site of insulin-mediated glucose uptake, and previous PCOS data have shown an intrinsic defect in insulin receptor signaling as a potential mechanism of insulin resistance, which may explain the negative impact on muscle mass reported in some studies." (PMID 37796920, 2023). "Since type 2 diabetes is preceded by a period of insulin resistance, hyperinsulinemia may confer a protective effect on BMD, either directly through elevated fasting insulin as demonstrated in diabetic and non-diabetic elderly men and women or indirectly through BMI." (PMID 37268885, 2023). "The reported analysis supports the hypothesis that if hypogonadal patients who still have active insulin (IS) are treated with TRT, IS will not worsen and lead to insulin resistance (IR) such that the metabolic pathways related to testosterone and insulin cannot be easily recovered." (PMID 37367840, 2023). "Here, obese GRLysMCre mice showed severe insulin resistance in comparison to GRflox mice shown by insulin tolerance test and a decrease in muscle tissue AKT phosphorylation upon insulin injection, while insulin response in lean mice was indistinguishable between genotypes." (PMID 37080971, 2023). "However, despite the lack of difference in body weight, HFD-fed Tmem135-AKO male mice exhibited glucose intolerance and insulin resistance, suggesting that adipose-specific TMEM135 inactivation has a primary effect on insulin sensitivity, independent of body weight difference." (PMID 37773161, 2023). "Homeostatic model assessment of insulin resistance (HOMA-IR) is currently the most widely used non-invasive measurement approach in clinical practice, but the application of this approach in patients with impaired β-cell function and insulin therapy is not ideal." (PMID 37138277, 2023). "In addition, serum insulin and glucose levels were unchanged (p = 0.5631) and increased non-significantly (p = 0.0531), respectively, in NAFLD patients compared to non-NAFLD individuals, indicating insulin resistance in NAFLD patients." (PMID 37670786, 2023). "Notably, genera within Proteobacteria were negatively associated with multiple metabolic parameters (HOMA-IR, fasting serum insulin, low-density lipoprotein, triglycerides, and total cholesterol) and CRP and Akkermansia had negative correlations with weight, insulin resistance, and CRP." (PMID 35316158, 2022).
Insulin resistance (continued). "The importance of JNK in insulin resistance has been addressed in different ways; for example, with gene knockout technology, the deletion of JNK1 in adipocytes has been found to inhibit insulin resistance, whereas the lack of JNK2 was found to “boost” the sensitivity to insulin at a cellular level." (PMID 35682832, 2022). "TNF-α and IL-1β are pro-inflammatory cytokines and are known to have negative effects on the action of insulin, such as impairing glucose uptake by inhibiting the phosphatidylinositol-3-kinase (PI3K) and protein kinase B (Akt) pathway and promoting the de-elopement of insulin resistance." (PMID 36145139, 2022). "The reported analysis supports the hypothesis that if hypogonadal patients who still have active insulin (IS) are treated with TRT, IS will not worsen and lead to insulin resistance (IR) such that the metabolisms related to testosterone and insulin cannot be easily recovered." (PMID 36361519, 2022). "For the patients with poor glucose control, homeostasis model assessment for insulin resistance (HOMA-IR), quantitative insulin sensitivity check index (QUICKI), and such may not be applicable under the interference from high blood glucose, impaired islet function and antihyperglycemic drugs." (PMID 36238131, 2022). "Injection of APS into the SMs of non-insulin-dependent type 2 diabetic KKAy mice ameliorated insulin resistance and hyperglycemia, and reduced MSTN levels in SM, which demonstrated APS might improve insulin sensitivity and reduce SM MSTN levels by downregulating the ROS-ERK-NF-κB pathway." (PMID 35812316, 2022). "Although no statistical differences were observed in fasting insulin concentrations and HOMA-IR among all groups, there was a trend toward higher HOMA-IR in the LBW-CHF group when compared to all other groups (P-model = 0.08) suggesting early signs of insulin resistance." (PMID 35782930, 2022). "Contrary, other studies were not able to identify any defects in skeletal muscle insulin signalling during euglycaemic-hyperinsulinaemic clamps or insulin stimulation in myotubes despite the given population of overweight and lean women with PCOS having severe insulin resistance." (PMID 34707569, 2021). "There is evidence that triglycerides alone are unlikely to directly affect insulin function, and we believe that regulation of DAG levels to alleviate insulin resistance may be one of the important channels for DOP to restore hepatic lipid metabolism disorders." (PMID 35155528, 2021). "However, other studies showed that upregulation of SIRT1 in skeletal muscle cells does not increase the total energy expenditure or enhance insulin sensitivity in mice fed a normal diet or HFD, nor does SIRT1 overexpression alters glucose-induced insulin resistance in rats." (PMID 33806509, 2021). "However, replacing saturated fatty acids or carbohydrates with polyunsaturated fatty acids lowered fasting glucose levels and glycated hemoglobin (HbA1C) and improved insulin resistance (HOMA-IR), but did not affect fasting glucose or postprandial glucose and insulin levels." (PMID 33264277, 2020). "However, insulin resistance in women with PCOS has been attributed to increased insulin receptor and insulin receptor substrate 1 (IRS1) serine phosphorylation in muscle, with impaired insulin signaling that affects the metabolic but not the mitogenic pathway." (PMID 33467251, 2020). "As IGF-I promotes insulin sensitivity, this increase in circulating IGF-I may compensate for the lack of IGFBP-1 and explain why IGFBP-1-KO do not display impaired glucose tolerance or insulin resistance in line with population data in the literature." (PMID 32190801, 2020). "We utilized measures that largely reflect hepatic insulin resistance (i.e., fasting insulin and glucose) to calculate HOMA-IR, which does not capture peripheral insulin resistance (i.e. skeletal muscle) which is thought to be the primary location for insulin resistance in CKD." (PMID 30786864, 2019).